IL10 (interleukin 10)
Diseases named in the same sentence as IL10 in open-access papers (continued):
Sharing a sentence is not in itself a finding about the gene and the disease.
COVID-19 (continued). "IL-10-mediated hyperactivation of CD8+ T cells despite an overall reduced cell count may also explain why some studies report functional exhaustion of T cells in severe COVID-19 cases and significant inverse associations between serum IL-10 levels and T cell count." (PMID 34234779, 2021). "The measurement of IL-10 and IL-12 (p70) levels on admission may be useful for the identification of hypertensive patients at greater risk of COVID-19 progression, particularly in the presence of classical clinical comorbidities (obesity, diabetes, and extensive lung involvement)." (PMID 34386533, 2021). "Moreover, because LPS is a known inducer of IL-10 production in macrophages, high levels of LPS may play a causal role in the observed elevations in IL-10 during COVID-19." (PMID 34234779, 2021). "The mechanism underlying the elevated COVID-19 mortality in patients with diabetes may be explained by the increase in chronic inflammatory markers, such as C reactive protein, interleukin 6, interleukin 10, and tumor necrosis factor-α, which promote susceptibility to COVID-19." (PMID 34940517, 2021). "Increasing IL-10, Th1 suppression, and suppression of IL-6 level by tocilizumab used during the cytokine storm period increase the risk of invasive pulmonary aspergillosis, which progresses with a cavity and has a very poor prognosis in the follow-up period in COVID-19 patients." (PMID 34284532, 2021). "In addition, PTGIS possesses anti-inflammatory properties by modulating the expression of interleukin-1 (IL-1), IL-6, and IL-10, which may be associated with COVID-19 severity." (PMID 34315889, 2021). "Notably, the association of early IL-10 production with COVID-19 severity supports this idea." (PMID 34434199, 2021). "Additionally, by using both LASSO model and XGBoost ML algorithm, we were able to validate previous results like age, disease severity, hs-CRP, and LDH were significant death risk markers for COVID-19 and further provide direct evidence for the fatal effects of serum ferritin and IL-10." (PMID 33410720, 2021). "In addition, our data suggested that lymphocytopenia, and increased levels of hsCRP, D-dimer, LDH, IL-6, and IL-10 were associated with severity and disease course of COVID-19 and might indicate a poor therapeutic efficacy." (PMID 33811756, 2021). "However, severe cases of COVID-19 have been associated with high levels of IL-10." (PMID 33071815, 2020). "Remarkably, patients with severe COVID-19 maintained significantly higher systemic IP-10, IL-1RA, IL-10, IL-15, and MIP-1β levels and mucosal IL-1RA, IL-12p40, and fractalkine through recovery and convalescence." (PMID 41313205, 2026). "Consistently, increased levels of T-cell-related cytokines (IL-2, MIP-1α, MIP-3α, IL-10, Eotaxin, IL-8, IL-17A–D, and IL-22) have been found in plasma of individuals with DS; among them IL-10 and IL-8 are upregulated in severe COVID-19." (PMID 41490093, 2026). "In 2022, a study compared different phenotypic patients, comparing patients in the intensive care unit and COVID-19 patients with neurological deficits showing increased IL-10 levels, while the opposite changes were observed, marking BBB disruption." (PMID 41516418, 2026). "At Day 1, COVID-19 exhibited significantly higher IL-6, IL-10, and CXCL10; FluA showed an attenuated cytokine response." (PMID 41683886, 2026). "For genes overlapping between SLE and COVID-19 severity, enrichment was observed in pathways related to interleukin-10 (IL-10) production, cytokine-cytokine receptor signalling, and the NOD-like receptor signalling pathway." (PMID 40643149, 2025). "A key aspect of severe COVID-19 is the overactive host-defence response, often called “cytokine storm,” Where cytokines that promote inflammation, like IL-6 and IL-10, significantly influence disease progression." (PMID 41585373, 2025). "Longitudinal studies have shown that cytokines such as IL-6 and IL-10 can also be used as markers of liver injury severity in patients with COVID-19." (PMID 41002992, 2025).
COVID-19 (continued). "Moderate and severe COVID-19 patients showed the highest percentage of overlap with high levels of IL-10 and IL-6 and TNF-α (47 % and 58%, respectively)." (PMID 40508859, 2025). "Our data are concordant with other publications that suggest the relevance and importance of monitoring circulating levels of IL-6 and IL-10 as useful predictors of early diagnosis for severe COVID-19 patients." (PMID 40508859, 2025). "Critical COVID-19 cases showed higher levels of inflammatory markers (Bilirubin, D-dimer, PCR, and urea, as well as IL-8, IL-10, TNF-α, INF-α, IL-1β, IL-17A, IL-23, IL-6) than moderate and severe groups." (PMID 39861879, 2025). "Hematological indices (neutrophil count and NLR), CRP, and serum IL-10 hold promise in monitoring ARDS severity in COVID-19 patients." (PMID 40761632, 2025). "COVID-19 patients with the IL-10 –1,082 A/G SNP, especially those with GG and AG genotypes and G allele, experienced less severe ARDS." (PMID 40761632, 2025). "Similar results were reported by Huang and colleagues, who reported increased circulating levels of IL-6 and IL-10 in critical COVID-19 patients." (PMID 40508859, 2025). "This includes a wide range of cytokines (such as interferon-γ, interferon-α, interleukin-8 and interleukin-10) and chemokines (such as chemokine ligands 9, 10 and 11), which act as important players in COVID-19 immunopathology." (PMID 40283188, 2025). "The largest significant difference was observed for IL-10 when comparing non-COVID-19 patients to COVID-19 patients with moderate and severe symptoms." (PMID 40508859, 2025). "The MR results for IL-10, interleukin-10 (IL-18) and programmed death ligand-1 (PD-L1) with COVID-19 demonstrated P values of <.05 for IVW, and revealed consistent causal effects across the 5 methods employed." (PMID 40101060, 2025). "IL-10 has been shown to play a part in COVID-19 pathogenesis, both during acute infection and post/long COVID-19." (PMID 41227320, 2025). "Overall, these findings support a protective association between the IL-10 –1,082 G allele and the severity of ARDS in COVID-19 and underscore the value of adjusted logistic regression analyses in accurately identifying genotype–phenotype relationships." (PMID 40761632, 2025). "As for IL-10, a distinctive characteristic of the cytokine storm in COVID-19 is the noticeable elevation of IL-10." (PMID 40143288, 2025). "We further characterized macrophage M2-type polarization in COVID-19 patients by measuring the expression levels of IL-10, Arg-1, TGF-β, and VEGF in plasma." (PMID 40160824, 2025). "Compared to the control group, COVID-19 patients showed significantly higher levels of IL-6, IL-10, IL6/IL-10 ratio, and miR-155 relative expression (p-values < 0.001)." (PMID 41203712, 2025). "Whilst exploring some of the other genes affected by COVID-19, we also found that the IL-10 gene was hypomethylated in COVID-19 patients at inclusion/hospitalization, indicating an active IL-10 response early on during infection." (PMID 41227320, 2025). "Several studies reported elevation of serum IL-6 and IL-10 in COVID-19 patients, and this elevation was dramatic with severe COVID-19 due to hyperactivation of the humoral immune system." (PMID 41203712, 2025). "In severe COVID-19, elevated levels of cytokines such as TNF-α, IL-6, IL-8, and IL-10 have been significantly associated with a reduction in T-cell counts." (PMID 41002992, 2025). "In this study we evaluated if levels of biomarkers including IL-10 can predict mortality if measured prior to ECMO initiation in patients with COVID-19 ARDS." (PMID 41339723, 2025). "We suggest that measuring circulating levels of IL-6 and IL-10 should be implemented and routinely quantified for patients with pneumonia and suspected COVID-19." (PMID 40508859, 2025).
COVID-19 (continued). "Extracellular ISG15 acts as a ligand for integrin ITGAL38, interacting with it and stimulating release of IFNγ and IL10 from NK cells through that interaction, with expression of IL10 being especially notable as an important factor in COVID-19 prognosis." (PMID 40374692, 2025). "We found that IL-6, IL-10, IL-6/IL-10 ratio, and miR-155 expression levels were significantly higher in COVID-19 patients than in healthy controls (p-values < 0.001)." (PMID 41203712, 2025). "IL-6, IL-10, IL-6/IL-10 ratio, and miR-155 expression were evaluated by ROC curve analyses for prediction ability for COVID-19 severity and mortality." (PMID 41203712, 2025). "Collectively, these findings underscore LDH’s critical role in mortality prediction, with P/F and IL-10 as key determinants of LDH increases in this Italian COVID-19 cohort." (PMID 40143288, 2025). "In conclusion, our study contributes to the growing evidence highlighting the elevation of inflammatory cytokines with their derived ratio (IL-6/IL-10) and miR-155 expression in COVID-19 patients." (PMID 41203712, 2025). "When laboratory data were compared according to COVID-19 severity, IL-6, IL-6/IL-10 ratio, and miR-155 expression showed the highest values in the severe group while serum IL-10 reached its lowest level in the severe group." (PMID 41203712, 2025). "The aim of this work was to evaluate the associations of polymorphisms in the TNF-α, IL-6, IL-8, IL-10, CCL5 and CXCL6 genes with COVID-19 outcomes and with the serum levels of IFN-α, IFN-γ, TNF-α, IL-1Ra, IL-6, IL-7, IL-10, CCL2, CCL3, CXCL8, CXCL10 and GCSF." (PMID 40881695, 2025). "On the other hand, serum IL-10 at a cut-off of ≤ 36 pg/mL was the best predictor for COVID-19 mortality." (PMID 41203712, 2025). "The association between IL-10 –1,082 A/G polymorphism and the severity of ARDS in COVID-19 patients was evaluated using both unadjusted (chi-square) and adjusted (logistic regression) analyses." (PMID 40761632, 2025). "In COVID-19 patients, there were too much of certain proteins called cytokines, including IL-1β, IL-1RA, IL-7, IL-8, IL-9, IL-10, basic FGF, G-CSF, GM-CSF, IFN-γ, IP-10, MCP-1, MIP-1A, MIP-1B, PDGF, TNF-α, and VEGF." (PMID 40895261, 2025). "Cystatin C also influences the release of key inflammatory mediators such as TNF-α, IL-12, IL-10, and nitric oxide, contributing to inflammation and potential multi-organ failure in severe COVID-19 cases." (PMID 40649865, 2025). "Our findings revealed a notable elevation of IL-10 in COVID-19 patients who developed organ failure compared with those without organ failure, consistent with previous literature that highlights IL-10’s role in severe disease progression." (PMID 41585373, 2025). "Previous reports have shown that the pathogenesis of COVID-19 is supported by a potent inflammatory response involving various mediators, such as IL-6 and IL-10." (PMID 41583455, 2025). "The proinflammatory cytokines IL-6 and IL-10 were significantly increased in COVID-19 patients compared to non-COVID-19 patients (p < 0.005), while TNF-α levels were lower in critically ill patients with COVID-19 pneumonia." (PMID 40508859, 2025). "This study was conducted to investigate the associations between polymorphisms in the TNF-α, IL-6, IL-8, IL-10, and CCL5 genes and COVID-19 severity." (PMID 40881695, 2025). "During acute COVID-19, CD25 levels were positively associated with several serum inflammation markers, including C-reactive protein (CRP), IL-1β, IL-6, IL-10, and tumor necrosis factor (TNF)." (PMID 41310351, 2025). "These markers reflect the immune dysregulation and hyperinflammatory states that exists in severe COVID-19, confirming IL-6’s central role and extending attention to IL-10, IL-8, and S100B as complementary markers of disease severity." (PMID 41585373, 2025). "They found that the mean concentration of circulating IL-10 was higher in deceased COVID-19 patients compared to those in COVID-19 patients who survived." (PMID 40508859, 2025).
COVID-19 (continued). "IL-6 and IL-10 levels were significantly elevated in COVID-19 patients suffering from pneumonia or organ failure." (PMID 41585373, 2025). "In this study, augmented IL-10 plasma levels were observed in COVID-19 hospitalized patients, with the highest level occurring during the critical phase of the disease (ARDS or pulmonary fibrosis)." (PMID 40160824, 2025). "In the current study, we found that serum IL-6, IL-10, and IL-6/IL-10 ratio were significantly higher in COVID-19 patients than controls." (PMID 41203712, 2025). "Analysis of the association between IL-10 -1082 A/G polymorphism and the severity of ARDS in COVID-19, considering both adjusted and unadjusted effects." (PMID 40761632, 2025). "This hyperactive immune response is characterized by the overproduction of inflammatory cytokines such as IL-6, IL-8, and IL-10, which are notably elevated in severe cases of COVID-19, contributing to immune dysregulation and increased disease severity." (PMID 40497938, 2025). "Despite its anti-inflammatory nature, IL-10 is also markedly increased in acute COVID-19 patients, reflecting a broader dysregulation of the immune system." (PMID 41585373, 2025). "Studies have shown that recombinant IL-10 can be utilized to exhibit anti-fibrotic activity and modulate immune-regulating functions in patients with COVID-19." (PMID 40552037, 2025). "This meta-analysis underscores the potential of IL-6, IL-10, and S100 proteins as important biomarkers in evaluating COVID-19 severity, offering valuable insights to help clinical management." (PMID 41585373, 2025). "The current study aimed to spotlight the interplay between miR-155 expression levels and inflammatory cytokines IL-6 and IL-10 with their derived ratio in the context of COVID-19 severity and mortality." (PMID 41203712, 2025). "Our findings corroborate previous studies reporting anxiety (27.3%) and depression (39%) in hospitalized COVID-19 patients, with both conditions correlating with longer hospital stays and elevated inflammatory markers (D-dimer, IL-6, IL-10)." (PMID 40087795, 2025). "Several studies have demonstrated that high levels of IL-10 lead to poor outcomes in COVID-19 patients, which is in line with the findings of our study." (PMID 40292283, 2025). "Concurrently, interleukins like IL-6, IL-8, IL-10, IL-17, and IL-1β are vital mediators of inflammation and have been shown to correlate with the severity of the disease in COVID-19 cases." (PMID 41585373, 2025). "SARS-CoV-2 did not induce significant IFN-α response or secretion of proinflammatory cytokines in the serum in the adult COVID-19 patients though the levels of IL-6, IL-8, IL-17, and IL-10 moderately increased." (PMID 39967737, 2025). "Our results showed that the expression of ACE2 was significantly up-regulated in COVID-19 patients and exhibits a significant correlation with IL-10." (PMID 40160824, 2025). "Despite previous constraints, in this study, the only one of its kind in Iraq robustly assesses COVID-19 ARDS severity using genetic markers (IL-10 SNP)." (PMID 40761632, 2025). "A positive significant correlation between COVID-19 and 2 inflammatory proteins were suggested: IL-10 (OR = 1.18, 95% CI: 1.04–1.34, P = .01) and IL-18 (OR = 1.19, 95% CI: 1.04–1.36, P = .01)." (PMID 40101060, 2025). "SNPs in the TNF-α, IL-6, IL-8, IL-10, CCL5 and CXCL6 genes have been associated with COVID-19 outcomes and with serum cytokine and chemokine levels." (PMID 40881695, 2025). "A major observation in this meta-analysis is the significant relationship between elevated interleukin levels, mainly IL-6 and IL-10, and adverse COVID-19 outcomes." (PMID 41585373, 2025). "These genes are involved in critical signaling pathways, including the COVID-19 adverse outcome pathway, pro-inflammatory and pro-fibrotic mediator pathways, and the IL-10 signaling pathway." (PMID 40166075, 2025).
COVID-19 (continued). "A study indicated that the inflammatory profile (CRP, IL-10, IL-17, IL-6, TNFα, and IL-1β) observed during the acute phase of severe COVID-19 predicts future long COVID symptoms." (PMID 40048451, 2025). "Similar patterns have been observed in COVID-19 patients, where elevated levels of IL-4, IL-10, and TNF-α were detected in serum samples." (PMID 41316426, 2025). "Taken together, an early change in the IL-6:IL-10 axis, captured succinctly by DBS, complements WHO-CPS and enhances short-term risk stratification in moderate-to-severe COVID-19." (PMID 41322840, 2025). "IL-10 was the single parameters presenting lower median levels in cord blood as compared with mother serum throughout convalescent COVID-19." (PMID 40821818, 2025). "The Dublin-Boston score (DBS) is a biomarker that captures the four-day change in IL-6:IL-10 and was shown to predict short-term clinical status in moderate-to-severely ill COVID-19 patients in the first week of hospitalization." (PMID 41322840, 2025). "Plasma levels of SARS-CoV-2 N antigen are associated with RAGE, IL-10, and IFN-gamma-inducible protein 10 kD (IP-10) levels, suggesting a role in modulating the progression to severe disease in hospitalized COVID-19 patients." (PMID 40872762, 2025). "In studies related to suppression of cytokine storms in the management of COVID-19, it was found that MSCs-Exo stimulated the release of IL-4, IL-10, and TGF-β." (PMID 40223864, 2025). "The enrichment analysis of these hub genes demonstrated that they are highly correlated with the adverse outcome pathway of COVID-19, the overview of pro-inflammatory and pro-fibrotic mediators, and the interleukin-10 signaling pathway." (PMID 40166075, 2025). "Serum from patients with severe COVID-19 induced increased levels of IL-1α, IL-1Ra, IL-5, IL-6, IL-10, IL-12(p40), IL-18, IL-27, and TNF-α." (PMID 41583455, 2025). "Among 39 patients with moderate-to-severe COVID-19 (24 declined by day four), the change in IL-6:IL-10 captured by the DBS strongly predicted short-term outcome." (PMID 41322840, 2025). "The elevated levels of IL-10 in severe COVID-19 cases offer intriguing insights into the cytokine dynamics at play within the disease’s pathogenesis." (PMID 39203987, 2024). "This implies the crucial role of IL-10 in managing COVID-19 severity by counterbalancing the inflammatory response." (PMID 38909235, 2024). "Stimulation of peripheral blood mononuclear cells from COVID-19 patients with helminth antigens is associated with reduced IFN-γ and TNF-α production and higher IL-10 levels." (PMID 38727220, 2024). "TNF-α, IL-8 and IL-10 are key cytokines in COVID-19 pathogenesis, and CXCR-2 is a major chemokine receptor involved in inflammatory response." (PMID 38544825, 2024). "The polymorphisms in TNFα -308 G>A (rs1800629), IL-8 -251T>A (rs4073), IL-10 (-1082 G>A), rs1800896 and CXCR2 +785 C>T (rs2230054) are associated with the risk of susceptibility to COVID-19 and with mortality in COVID-19 patients." (PMID 38544825, 2024). "High granulocyte colony-stimulating factor (G-CSF) levels are detected in parallel with elevated serum levels of IL6 and IL10 in severe COVID-19." (PMID 38543303, 2024). "Other studies found upregulated IL-35 and IL-10 transcripts in the Tregs of patients with severe COVID-19." (PMID 39597537, 2024). "This study aimed to evaluate the association of the levels of cytokines interleukin (IL)-2, IL-6, tumor necrosis factor-alpha (TNF-α), interferon-gamma (IFN-γ), and IL-10 with the severity of COVID-19 in Bangladesh." (PMID 38707035, 2024). "ROC analysis revealed that IP-10, MCP-1, sTREM-1, and IL-10 had significant value in distinguishing COVID-19 patients with different clinical outcomes." (PMID 39654886, 2024).